PPARG (peroxisome proliferator activated receptor gamma)
Diseases named in the same sentence as PPARG in open-access papers (continued):
Sharing a sentence is not in itself a finding about the gene and the disease.
cancer (continued). "Combination therapies using EGFR inhibitors and PPARγ agonists show promising results against some urothelial tumors in vivo as well as against other cancers." (PMID 32822399, 2020). "In summary, our results demonstrated that PPARγ inhibits the proliferation and metastasis of this malignant tumor by inhibiting LEF1/β-catenin signaling transduction by RT and PPARγ." (PMID 33289586, 2020). "The transactivation of PPARγ induces apoptosis and inhibits proliferation in human cancer cell lines." (PMID 32054125, 2020). "PPARγ activation by synthetic ligands has proven an effective anti-cancer regimen through the induction and maintenance of a more differentiated state and/or by apoptosis." (PMID 32958825, 2020). "Again, in the setting of colorectal cancer, it has been shown that PPARβ/δ overexpression or activation antagonizes PPARγ-induced apoptosis of cancer cells." (PMID 32375405, 2020). "The high frequency of mutations in helix H3 of the peroxisome proliferator-activated receptor gamma (PPARγ) ligand-binding domain (LBD) in various cancers suggest that this region has an important role in tumorigenesis." (PMID 33266062, 2020). "Previous studies showed that conjugated linoleic acid (CLA) was able to induce apoptosis, upregulate PPARG gene expression and activate PPARγ protein in certain human cancer cell lines." (PMID 31993929, 2020). "As exposure days to PGZ were increased, the expression level of GLUT4 and PPARγ was significantly (P < .05) increased in the differentiating A-549 cancer cells treated with 50 μM PGZ, compared with those of untreated control cells." (PMID 33456717, 2020). "PPARγ agonists induce apoptosis in these cancer cells through reduction of survivin, which in turn leads to apoptosis through increased caspase-3 activity." (PMID 32375405, 2020). "The results of the test for PPARγ also indicate an increase in expression of this factor in cancer cells after incubation with celecoxib." (PMID 31935820, 2020). "Mechanistically, the canonical Wnt/β-catenin pathway and PPARγ signaling work in an opposite manner in cancers generally creating a vicious circle." (PMID 33352766, 2020). "Regarding cancer prognosis, the results were surprisingly consistent in that amplification of PPARγ mattered greatly in longer survival time and reduced recurrence or progression 12, 14-18." (PMID 32328200, 2020). "PPARγ and androgen receptor are both ligand‐activated nuclear receptors with important roles in normal prostate development and cancer progression." (PMID 33031638, 2020). "An important study from the group of Michalik further cautions the risks of the use of thiazolidinedione PPARγ agonists in cancer patients." (PMID 32785018, 2020). "Compound 1 has also attracted considerable interest as a peroxisome proliferator-activated receptor γ (PPARγ)-mediated inhibitor of cancer cell proliferation (see reference 63 and references therein)." (PMID 32086307, 2020). "The PPARG gene is related to malignancy, which plays a vital role in the pathogenesis of multiple cancers in some clinical studies and animal models." (PMID 32265986, 2020). "Cell cycle arrest and stimulation of autophagy are two major processes by which PPARγ stops cancer cell progression, as evinced in the colon, breast, bladder, and adrenocortical cancer cell lines." (PMID 33198317, 2020). "The upregulation of peroxisome proliferator-activated receptor gamma (PPARG) has been shown to increase the chemosensitivity of several human cancers." (PMID 32373170, 2020). "The literature search was performed using the following keywords: “PPARγ” AND “cancer” obtaining 3774 papers." (PMID 32937951, 2020). "In this study, we evaluated the anti-cancer effect of CB13 (a novel PPARγ agonist candidate) and investigated the role of PPARɣ, ROS, exosomes, and ER stress in CB13-induced cell death in human NSCLC and radio-resistant NSCLC cells." (PMID 33051435, 2020).
cancer (continued). "Among the three PPAR isoforms (α, β/δ and γ), PPARγ plays a crucial role in adipogenesis and lipid metabolism and is also found expressed in many human cancers, including BC." (PMID 32085795, 2020). "From the forest plot, we found that PPARD and PPARG were of pan-cancer significance with HR > 1 in most cancer types." (PMID 33029111, 2020). "For this cancer, PPARg is also involved in inhibiting cell growth and attenuating cell migration and invasiveness." (PMID 32850012, 2020). "The results indicated a significant increase in PRODH/POX and PPARγ expression in cancer cells treated with various concentrations of celecoxib compared to controls." (PMID 31935820, 2020). "In a recent study, lung cancer cells treated with PPARγ agonists remarkably lost migratory and invasive properties essential for cancer metastasis." (PMID 33266062, 2020). "It has also been shown that T0070907 treatment has significant antitumor effects in various cancer cell types, and these effects are explained by the PPARγ pathway." (PMID 32294907, 2020). "Its lower concentration in lung tumors correlated with decreased activity of peroxisome proliferator-activated receptor gamma (PPARγ) and, as a result, with cancer development." (PMID 32349264, 2020). "Reka, Lecarpentier14 and Heudobler15 reviewed the implications for PPARγ in cancer therapy and prevention." (PMID 32031298, 2020). "In particular, genetic alterations of PPARγ found in various cancers have been reported to play important roles in tumorigenesis by affecting PPARγ transactivation." (PMID 33266062, 2020). "The pathologic changes of CDK5 and PPARγ in a various metabolic diseases and cancer have been well addressed." (PMID 32054125, 2020). "Signaling via the PPARγ pathway is essential for the growth arrest and terminal differentiation of adipocytes and other normal epithelial and cancer cells, whereas signaling via the EGFR receptor plays a role in cell proliferation." (PMID 32822399, 2020). "Positive immunoreactivity for PPARγ was detected in the nuclei of carcinoma cells and normal endometrial gland cells." (PMID 33197888, 2020). "When tested in vitro, dmrFABP5 suppressed the cancer cells by blocking fatty acid stimulation of PPARγ, and thereby prevented it activating down-stream cancer-promoting or inhibiting cancer-suppressing genes." (PMID 31258834, 2019). "Drugs against peroxisome proliferator-activated receptor-gamma (PPARγ) have been the subject of numerous studies because of their potential to treat a panoply of malignancies such as cancer." (PMID 31655621, 2019). "PPARγ was highly expressed in para-cancer (normal) tissues, as a nuclear factor predominantly located in the nucleus of cells." (PMID 30845932, 2019). "PPARγ agonists offer an interesting therapeutic solution in cancers by acting on both oxidative stress and inflammation." (PMID 31311204, 2019). "Preclinical studies have suggested a role for PPARγ and PPARβ/δ antagonists as anti-obesity and anti-cancer therapy, respectively." (PMID 31614690, 2019). "The molecular mechanisms through which PPARγ controls cancer initiation/progression depend on the different mode of binding of distinctive ligands." (PMID 30931956, 2019). "In cancer therapy, several studies have shown that PPARG activation exerts antiproliferative, apoptotic, differentiation, and antiangiogenic effects." (PMID 31319484, 2019). "More recently it was shown that in MDSCs, PPARγ plays a critical role in neutral lipid metabolism signaling controlled by lysosomal acid lipase (LAL) and that enhanced PPARγ activity impairs MDSCs-mediated proliferation and spreading of cancer cells." (PMID 31535085, 2019).
cancer (continued). "For other cancer types, some small molecule agonist of PPARγ has been shown to reduce the phosphorylation of Akt at Ser473 and exert therapeutic effects." (PMID 30845932, 2019). "These in vivo and ex vivo data suggest that the early injection of apoptotic cancer cells results in a shift in TAMs to an antimetastatic phenotype, leading to the PPARγ-dependent production of PTEN and its ligands." (PMID 30842627, 2019). "Few studies have focused on the potential role of WNT and PPARγ with circadian clocks in cancer development." (PMID 31331376, 2019). "On the other hand, ligand-activated PPARγ facilitates terminal differentiation, promotes cell cycle arrest, and apoptosis of cancer cells." (PMID 31614690, 2019). "In short, both PPARγ and PPARβ/δ in CAFs play a significant modulatory role in cancer development, of which the former acts on the local inflammation and cancer invasiveness while the latter alters the redox balance in TME." (PMID 30925918, 2019). "The non-steroidal anti-inflammatory drugs (NSAID)-dependent inhibiton of COX-2 and activation of PPARγ has been shown to suppress cancer stem cells in colon cancer." (PMID 30424016, 2018). "PPARG, a subtype of PPAR superfamily, predominantly regulates metabolic changes associated with lipid and carbohydrate homeostasis that affect cancer cell growth." (PMID 30510575, 2018). "An increasing number of studies have focused on the effect of PPARγ in cancer using natural and synthetic ligands for PPARγ and overexpression experiments." (PMID 29599799, 2018). "All these complex and opposing interactions between the canonical WNT/β-catenin pathway and PPARγ appear to be fairly common in inflammation, oxidative stress, and cancers." (PMID 29706964, 2018). "The previous study has suggested that the inhibition of cell growth can results in the activation of PPARγ in several in vitro cultured human cancer cell lines." (PMID 30460096, 2018). "In fact, it has been reported that TZDs also exert anti-cancer effects through a PPARγ-independent mechanism by triggering intracellular calcium flux, inhibition of translation, and cell cycle arrest." (PMID 29932104, 2018). "Celecoxib suppresses cancer stemness and the progression of hepatocellular carcinoma via activation of PPARγ and up-regulation of PTEN." (PMID 30424016, 2018). "In contrast, peroxisome proliferator-activated receptor gamma (PPARγ) is downregulated in numerous cancers." (PMID 29706964, 2018). "The opposite is observed with PPARγ, which is generally downregulated during inflammation and oxidative stress and in many cancers." (PMID 29706964, 2018). "PPARγ is a critical player in the regulation of glucose metabolism, lipid storage, inflammation, cancer, and the regulation of whole body energy homeostasis." (PMID 29382850, 2018). "Several recent studies have shown that PPARγ agonists inhibit the survival of cancer stem cells (CSCs)." (PMID 29599799, 2018). "The peroxisome proliferator-activated receptor γ (PPARγ) is a nuclear receptor that plays a key role in regulating cellular metabolism, and is a therapeutic target for cancer therapy." (PMID 30018246, 2018). "PPARγ has been identified in many cancers including those affecting the brain, where it regulates target gene transcription, and its activation inhibits tumor cell growth." (PMID 30405366, 2018). "In contrast, the silencing of PPARγ in cancer has the opposite effect on the activation of the cancer survival pathway." (PMID 30323259, 2018). "Understanding the role of PPARγ in cancer was improved by developing new synthetic and natural ligands of PPARγ and performing overexpression and knockdown experiments." (PMID 29599799, 2018). "By regulating lipid and glucose homeostasis, differentiation, ROS and inflammation, PPARγ agonists appear to offer interesting therapeutic solution in cancers." (PMID 29706964, 2018).
cancer (continued). "Among the three subtypes of PPARs, PPARγ modulates a broad range of physiopathological processes, including lipid metabolism, insulin sensitization, cellular differentiation, and cancer." (PMID 30012954, 2018). "PPARG has been reported to play a protective role in some types of cancer but play an oncogenic role in other types of cancer." (PMID 30510575, 2018). "Treatment with PPARγ agonists inhibits cancer cell growth by inducing G0–G1 cell-cycle detention, promoting differentiation and reverting the EMT." (PMID 29530037, 2018). "In cardiomyocytes and cancer cells, HIF1α has been reported to activate PPARγ.107, 108 In pulmonary vascular cells, PPARγ is reportedly subject to HIF1-dependent and HIF1-independent adjustment." (PMID 29929789, 2018). "To date, few studies have revealed PPARγ agonists to play a positive role in the inhibition of invasion and the migration of cancer cells." (PMID 29706964, 2018). "Epirubicin inhibits DNA and RNA synthesis by intercalating DNA strands and Topotecan inhibits cancer cell differentiation through PPARγ degradation, which disturbs the normal processes of cell division and differentiation, and impedes cell damage repair." (PMID 27835912, 2017). "In cancer models, PPARγ activation decreases PI3K activity by modulating PTEN protein expression, suggesting its role in the regulation of the autophagic process as well." (PMID 28932171, 2017). "Taken together, these data clearly highlight the potent effect of PPARγ to modulate lipid metabolism, especially de novo lipid synthesis subsequently suppress cancer growth." (PMID 29137280, 2017). "High concentrations of PPARγ agonists, including RGZ, have been implicated to induce lysosomal degradation processes in cancer cells, for example autophagy." (PMID 29201005, 2017). "Exposure to PPARγ agonists such as TZD has been shown to trigger apoptosis in a variety of cancers using in vitro and animal models through PPARγ-dependent or -independent mechanisms." (PMID 29296202, 2017). "Taken together, this study provides an insight of insulin sensitizers-mediated cancer metabolism into understanding the prognostic benefit as well as therapeutic potential of the PPARγ in the cancer clinic." (PMID 29137280, 2017). "Rosiglitazone downregulates PI3K as it belongs to thiazolidinedione class of drugs which are potentially useful in treating several cancers through both PPARγ-dependent and PPARγ-independent mechanisms." (PMID 28642704, 2017). "The potential of using PPARγ as a direct target for cancer treatment has been widely investigated during the past decade but still remains debatable." (PMID 28415688, 2017). "In fact, many studies in cancer therapy employ pharmacological agonists of PPARγ with the aim of promoting a slow down of the cell cycle." (PMID 29020973, 2017). "More than 30 PPARγ natural variants are reported in COSMIC, a database designed to store and display somatic mutation information relating to human cancers." (PMID 28208577, 2017). "Among the 606 cancer-related miRNAs, eight were targeting PPARα, four were targeting PPARβ/δ, and eight were targeting PPARγ." (PMID 28167956, 2017). "In particular, PPARγ isoform was shown to reduce cancer cell proliferation as well as regulate cell differentiation, activate apoptosis, and inhibit angiogenesis." (PMID 28458685, 2017). "This avoids the fatty-acid stimulation of PPARγ and prevents it activating the down-stream regulated cancer-promoting genes." (PMID 28415688, 2017). "In fact, due to the versatile nature of PPARγ in its biological function, targeting PPARγ directly for cancer treatment is also difficult to achieve." (PMID 28415688, 2017). "FuOH suppressed key molecules responsible for cancer survival and tumorigenesis in Csps, such as pAkt (Ser473), PPARβ/δ, and PPARγ." (PMID 28751806, 2017). "PPARγ is a nuclear receptor that regulates differentiation and proliferation and is highly expressed in many cancer cells." (PMID 28642874, 2017).
cancer (continued). "We focus this review on the interactions between the canonical WNT/beta-catenin pathway and peroxisome proliferator-activated receptor gamma (PPAR gamma) in cancers and their implications from an energetic and metabolic point of view." (PMID 28405929, 2017). "Several cancers have shown reduced growth with PPARγ activation with the TZD troglitazone such as in carcinomas of the breast, kidney, liver, colon, pancreas, and prostate as well as in non-small-cell lung cancer and ACTH-secreting pituitary adenomas." (PMID 28348577, 2017). "Paradoxically, molecules with PPARG antagonist actions are able to inhibit invasiveness and proliferation of some cancer cell lines." (PMID 27579030, 2016). "Previous studies have proposed that activation of PPARγ by RGZ inhibits growth of various types of cancer." (PMID 27323819, 2016). "Though the roles of PPARγ in cancer therapy are debatable, accumulating evidence suggested that activation of PPARγ by agonists exerts an inhibitory effect on cancer cells." (PMID 27323819, 2016). "The essential contribution of PPARγ to metabolic regulation in multiple organs suggests potential roles in the intestine other than those already described in inflammation and cancer." (PMID 27853235, 2016). "There is some evidence linking PPARG agonist's actions to better cancer treatment responsiveness as well." (PMID 27579030, 2016). "The investigated pirinixic acid derivatives modulate 5-LO, mPGES1, PPARα, and PPARγ at varying potencies and these molecules are considered as potential anti-cancer drug targets." (PMID 26887049, 2016). "Peroxisome proliferator-activated receptor γ (PPARγ) is a ligand-activated nuclear receptor that regulates cellular lipid and glucose metabolism and also plays an inhibitory role in various cancers." (PMID 27483249, 2016). "The cyclopentenone prostaglandin 15-deoxy-Δ12,14-prostaglandin J2 (15d-PGJ2) is a natural ligand of peroxisome proliferator-activated receptor gamma (PPAR-γ) and a potential mediator of apoptosis in cancer cells." (PMID 27190500, 2016). "As a complementary approach to our loss-of-function genetic approach, we next performed gain-of-function pharmacological experiment to assess the effect of rosiglitazone activation of macrophage PPARγ on cancer cells." (PMID 27692066, 2016). "PPARγ agonists also demonstrate a synergistic effect with traditional chemotherapeutic agents, enhancing their cytotoxic effect on cancer cells." (PMID 27698657, 2016). "This suggests that as happens with vitamin D, advanced cancer stages can epigenetically repress PPARG expression and then nullify its antineoplastic actions." (PMID 27579030, 2016). "Accumulating evidence indicates that PPARγ plays a critical role in cancer cell growth, migration, invasion, and apoptosis." (PMID 27483249, 2016). "In the following paragraphs, we will review what we know about the specific molecular actions of PPARG in cancer biology." (PMID 27579030, 2016). "To understand how PPARγ alters the transcription program in macrophages to control cancer cell proliferation, we next set out to identify the key PPARγ target genes." (PMID 27692066, 2016). "Significantly, TZD action appears to be restricted to the high Sox2 expressing cancer stem cell population and is dependent on PPARγ expression." (PMID 27528232, 2016). "Although most research on PPARG has been focused on its metabolic action, some of them are neurogenesis, osteogenesis, cancer, or cardiovascular disease." (PMID 27579030, 2016). "Review of extensive experimental data combined with retrospective analysis of human data supports PPARγ as a promising therapeutic target in cancer." (PMID 27698657, 2016). "Yet understanding pathways by which PPARγ contributes to the spread and progression of cancer in vivo, including its effects on immune cells is less well understood." (PMID 26625314, 2016).